ALB (albumin)
Diseases named in the same sentence as ALB in open-access papers (continued):
Sharing a sentence is not in itself a finding about the gene and the disease.
Pruritus (19 papers, 2009 to 2025). Pruritus is an itch or a sensation that makes a person want to scratch. "For instance, uremic toxins are linked with pruritus, and low albumin levels are associated with nail disorders and potentially undiagnosed conditions like porphyria." (PMID 38352109, 2024). "In the present study, lower serum albumin level was an independent factor associated with severe pruritus (NRS ≥5 points), suggesting that decrease in liver function could lead to severe pruritus in patients with chronic liver disease." (PMID 31651244, 2019). "Patients with pruritus had a higher prevalence of S. aureus nasal carriage compared to those without (32.7% vs. 13.3%; p = 0.02) and a higher level of serum albumin (4.1 vs. 3.9 g/dL; p = 0.02)." (PMID 40528508, 2025). "During the first pregnancy, UDCA therapy was interrupted leading to refractory pruritus requiring albumin dialysis." (PMID 37701337, 2023). "After further adjustments with anthropometric variables, fasting glucose, total cholesterol, glutamic pyruvic transaminase, uric acid, albumin, WBC count, and hs-CRP, the PCS concentration was still significantly associated with pruritus." (PMID 36983311, 2023). "The severity of pruritus was negatively correlated to total weekly Kt/V in PD patients and serum albumin levels in HD patients." (PMID 34437400, 2021). "In an international prospective cohort study on HD patients, the patients with pruritus were older, had higher median C-reactive protein, and had hepatitis B or C antibodies and low serum albumin." (PMID 34437400, 2021). "Secondly, they have protein-absorbing capacity and can absorb low and high molecular weight (HMW) proteins, probably pruritus-related molecules that weigh in the range of albumin or greater, which cannot penetrate sharp filters such as polysulfone membranes." (PMID 32408613, 2020). "Multivariable analysis identified higher eosinophil count (OR = 1.001; P = 0.002), lower albumin levels (OR = 0.637; P < 0.001), and PBC (OR = 2.065 for others; P = 0.004) as independent factors associated with severe pruritus." (PMID 31651244, 2019). "Conversely, herbal remedies used by HD patients may have numerous possible benefits such as decreasing cutaneous pruritus, oxidative stress status, muscle cramps, and dialysis frequency or reducing proteinuria and increasing serum albumin and haemoglobin." (PMID 27400742, 2016). "Albumin levels were associated with pruritus in all subjects, but not in PBC patients." (PMID 31651244, 2019). "Clearly, some genes such as AKT1, ALB, BCL2, STAT3, JUN, ESR1, and TNF hold important positions within the network, indicating their strong relevance to the pathogenesis of pruritus and their potential as key targets for drug intervention." (PMID 39606625, 2024). "Circulating branched amino acids were not significantly modified by albumin dialysis, whereas phenolic aromatic amino acids decreased markedly in patients with alcoholic hepatitis and increased in patients with pruritus." (PMID 19175915, 2009). "Furthermore, albumin dialysis with MARS is well tolerated, and can therefore be considered the last rescue step in patients with pruritus who did not experience favorable results with non-invasive treatments." (PMID 21779339, 2011).
scrub typhus (19 papers, 2010 to 2025). Scrub typhus is a rare dust mite-borne infectious disease caused by the Orientia tsutsugamushi bacterium and characterized clinically by an eruptive fever which is potentially serious. "Key predictors associated with both scrub typhus and doxycycline-treatable causes were age, illness duration, lymphadenopathy, oedema, hepatomegaly, lymphocyte count, platelet count, and serum albumin levels." (PMID 40672782, 2025). "Serum albumin level is helpful to predict the development and severity of scrub typhus-associated AKI." (PMID 33630937, 2021). "The albumin level of scrub typhus patients was greater than that of SLE patients (median 3.6 vs. 3.0 g/dL, P = 0.002)." (PMID 38961124, 2024). "Blood brain barrier (BBB) leakage, as measured by significantly higher albumin index in cerebrospinal fluid has been confirmed in scrub typhus patients." (PMID 37426673, 2023). "The patients with scrub typhus were divided into two groups based on the serum albumin levels; Group I (serum albumin <3.0 g/dL) and Group II (serum albumin ≥3.0 g/dL)." (PMID 20646323, 2010). "In scrub typhus patients, serum albumin levels fall and ANA titers rise." (PMID 39879248, 2025). "Therefore, it is especially important to check the serum albumin level to predict the clinical course and prognosis of patients with scrub typhus." (PMID 33630937, 2021). "Moreover, the increased albumin index was positively correlated with the expression levels of an astrocyte marker (glial fibrillary acidic protein), indicating the activation of astrocytes in the brain of scrub typhus patients." (PMID 37426673, 2023). "Multivariate analysis showed that age, presence of CKD, serum albumin level and time to hospital presentation after symptom onset were independent predictors of AKI in patients with scrub typhus." (PMID 28298367, 2017). "Clinical parameters indicated significant differences in direct bilirubin, total protein, albumin-to-globulin (A:G) ratio, and potassium levels between the scrub typhus-positive and negative groups." (PMID 40621267, 2025). "Both typhus forms demonstrated similar disease severities and complication rates, but the levels of albumin (reduced, but within the normal range) and CRP (elevated) in patients with scrub typhus suggest that inflammation might play a more important role in scrub typhus than in murine typhus." (PMID 22192733, 2012). "In summary, the results of this study suggest that clinicians should be aware of the potential for severe scrub typhus, when scrub typhus patients are older (≥ 60 years), present with the absence of eschar, or laboratory findings such as WBC counts > 10, 000/mm3, and serum albumin level ≤ 3.0 g/dL." (PMID 20433689, 2010). "Our results suggest that clinicians should be aware of the potential for complications, when scrub typhus patients are older (≥ 60 years), presents without eschar, or laboratory findings such as WBC counts > 10, 000/mm3, and serum albumin level ≤ 3.0 g/dL." (PMID 20433689, 2010).
alcoholic cirrhosis (18 papers, 2014 to 2025). "This meta-analysis evaluates three key laboratory parameters—serum albumin, total bilirubin, and platelet count—across etiologic subgroups of alcoholic and non-alcoholic cirrhosis, to assess their respective predictive performances." (PMID 40969799, 2025). "The Toronto group has identified MELD <20 and a serum albumin at the time of listing as the only independent predictors for successful delisting for patients with alcoholic cirrhosis." (PMID 37762820, 2023). "In conclusion, the risk of HCC can be stratified by using a combination of readily available clinical parameters (age, AFP level, and albumin level) in patients with alcoholic cirrhosis." (PMID 35110551, 2022). "The risk of HCC can be stratified by using a combination of readily available clinical parameters (age, AFP level, and albumin level) in patients with alcoholic cirrhosis." (PMID 35110551, 2022). "A more recent study showed that increased creatinine, bilirubin, MELD score and decreased serum sodium and albumin to be predictors of development on HRS in patients with alcoholic liver cirrhosis." (PMID 34884323, 2021). "In this retrospective study, we show that the NLR and blood ALB level are significantly correlated with disease progression and survival in alcoholic cirrhosis patients." (PMID 33415154, 2020). "In non-specialized units where transient elastography is not available, blood tests recommended for diagnosing compensated alcoholic cirrhosis include, in addition to the platelet count and serum AST and ALT used to calculate FIB-4 and APRI, INR and bilirubin, albumin, and serum creatinine." (PMID 37626629, 2023).
cardiomyopathy (18 papers, 2006 to 2026). A disease of the heart muscle or myocardium proper. "In addition, albumin levels <3500 mg/dl (HR 1.89; 95% CI 1.13–3.17), increasing age (HR 1.06 per year; 95% CI 1.03–1.09), and cardiomyopathy (HR 3.01; 95% CI 1.62–5.59) were associated with an increased risk for all-cause mortality." (PMID 23844107, 2013). "Recent studies have shown that reduction of bile acid concentrations (either through albumin‐charcoal dialysis or plasma exchange) can potentially provide a therapeutic means of reducing cardiomyopathy in these patients." (PMID 40999709, 2025). "The CTD database showed that the common hub genes (IGF1, MYH11, TGFB3, ALB, and AGT) were targets in cardiomyopathies." (PMID 35845066, 2022). "Lnc‐MEG3 expression was positively correlated with cardiomyopathy, APACHE II score, SOFA score, Scr, TNF‐α, IL‐1β, IL‐6, and IL‐17, 28‐day deaths, while negatively correlated with albumin." (PMID 34956235, 2021). "Compared with the marked BNP improvement group, the BNP worsening and no-marked BNP change groups had lower serum albumin, hemoglobin and eGFR and had a lower prevalence of cardiomyopathy etiology and β-blocker use and a higher proportion of diuretics use." (PMID 35089974, 2022). "From the autopsy reports, we concluded that none of the deceased with LVH or an elevated albumin/creatinine ratio suffered from cardiomyopathy or kidney disease." (PMID 29713389, 2018). "Patients that failed to achieve hemodynamic optimization goals exhibited increased 1-year mortality (HR 4.1, 95% CI 1.24–13.2, p = 0.02) adjusted for age, INTERMACS category, type of cardiomyopathy, creatinine, total bilirubin and albumin, compared with no RVD at baseline." (PMID 36294432, 2022).
Cerebral ischemia (18 papers, 2008 to 2024). Restriction of arterial blood supply to the brain associated with insufficient oxygenation to support the metabolic requirements of the tissue. "Enteral cilostazol and high-dose intravenous (IV) albumin have been associated with reduced angiographic vasospasm, cerebral ischemia, and death or disability in several clinical trials." (PMID 39553040, 2024). "Our findings highlight the therapeutic potential of enteral cilostazol and high-dose IV albumin combination for refractory cerebral ischemia associated with aSAH by potentially influencing multiple pathways." (PMID 39553040, 2024). "A combination of oral cilostazol and IV high dose (25%) albumin was associated with amelioration of angiographic vasospasm, reduction of tissue perfusion deficits, and clinical improvement of aSAH patients with severe refractory cerebral ischemia." (PMID 39553040, 2024). "Inhibition of PK led to significantly reduced extravasated albumin and PK in the brain parenchyma at day 7 after cerebral ischemia in αPK-treated mice." (PMID 38872149, 2024). "In aSAH patients who are on multiple treatments, the exact role of the combination of cilostazol and IV albumin in the amelioration of cerebral ischemia needs to be considered." (PMID 39553040, 2024). "It is possible that cerebral ischemia resolved spontaneously as part of the natural history of cerebral ischemia and vasospasm, but the time course of resolution correlated strongly with the initiation of enteral cilostazol and IV albumin." (PMID 39553040, 2024). "All patients were then administered enteral cilostazol (200 mg/day) and IV (25%) albumin (1.25 g per kg over eight hours) treatment for refractory cerebral ischemia." (PMID 39553040, 2024). "Most of animal studies have shown albumin to be a promising neuroprotectant in cerebral ischemia, traumatic brain injury and neurodegenerative disease." (PMID 36384553, 2022). "As exemplarily shown in a mouse with 72 hours (h) of filament-based focal cerebral ischemia, the immunoreactivity (ir) for albumin was visually enhanced and appeared with coarse deposits in the ischemic striatum (A’’’)." (PMID 35682557, 2022). "According to experimental cerebral ischemia studies, hyperoncotic albumin can reduce infarct volume and edema, augment cortical perfusion and improve functional outcome." (PMID 18318896, 2008). "A major limitation of our results is the small number of patients (n = 3) in our case series; the role of the combination of enteral cilostazol and IV albumin in the amelioration of cerebral ischemia needs to be explored in a larger case series and possibly in a randomized controlled trial." (PMID 39553040, 2024). "However, the integrity and barrier function of BBB are disrupted after cerebral ischemia, leading to water and albumin through the vascular within hours, and other potentially toxic and inflammatory substances in the plasma enter the brain parenchyma within several days." (PMID 35873558, 2022). "The results of network pharmacology suggest that catalpol is involved in the regulation of inflammation, vascular homeostasis, and vascular remodeling after cerebral ischemia, which is closely related to F2, MMP9, VEGF/KDR, and ALB." (PMID 33505489, 2021). "In this study, we compared BBB permeability to Evans blue dye (EBD), fluorescein, 10 kDa dextran-FITC, and endogenous albumin in mice subjected to dMCAO, which requires craniectomy, to that in mice subjected to craniectomy alone without induction of cerebral ischemia." (PMID 36224001, 2022).
chronic hepatitis B (18 papers, 2010 to 2025). "The following parameters were significantly (P < .2) associated with tumor necrosis by TACE in the univariate analysis: MVI, radiological capsule appearance on CT, chronic hepatitis B, DM, and serum albumin." (PMID 34232206, 2021). "In addition, both ALT and albumin have been found to be HCC predictors in chronic hepatitis B patients." (PMID 23613855, 2013). "No statistical differences were observed in age, sex, the percentage of chronic hepatitis B and chronic hepatitis C, and serum level of ALT, AST, total bilirubin, Na, BUN, Cr., and albumin between the derivation and validation data." (PMID 30240398, 2018).
chronic hepatitis C (18 papers, 2010 to 2025). "Interferon alpha-2b (IFN-α2b) is an essential cytokine widely used in the treatment of chronic hepatitis C and hairy cell leukemia, and serum albumin is the most abundant plasma protein with numerous physiological functions." (PMID 38473998, 2024). "Serum 25-hydroxyvitamin D3 levels in chronic hepatitis C Japanese patients were influenced by gender, age, hemoglobin level, albumin and the season of measurement." (PMID 26286329, 2015). "There were significant differences (P = 0.0001 for each) in the mean values of ALT, AST, prothrombin concentration, serum total bilirubin, serum albumin and platelet count between chronic hepatitis C patients and controls." (PMID 20300411, 2010). "After treatment, the serum levels of AST and ALT were decreased, and the platelet count and serum levels of albumin, HDL cholesterol and LDL cholesterol were increased in accordance with the cure of chronic hepatitis C (CHC)." (PMID 29777191, 2018). "Thus, in patients with chronic Hepatitis C, a reactive expression of the AFP gene, as shown in hepatic necroinflammation and hepatocellular proliferation, may be associated with a decrease in albumin gene transcription and may lead to a lower serum albumin level." (PMID 22675639, 2012).
diabetic neuropathy (18 papers, 2007 to 2025). A chronic, pathological complication associated with diabetes mellitus, where nerve damages are incurred due to diabetic microvascular injury involving small blood vessels that supply these nerves, resulting in peripheral and/or autonomic nerve dysfunction. "Furthermore, the association between albumin and diabetic neuropathy was found to be stronger in patients with a higher BMI (≥24 kg/m2) compared to those with a lower BMI (<24 kg/m2)." (PMID 38202194, 2023). "However, some studies suggest that increased urinary albumin might be a marker for endothelial damage, the function of which may be the common cause of both microalbuminuria and diabetic neuropathy." (PMID 17927826, 2007). "In animal studies, infliximab inhibited urinary albumin excretion in experimental diabetic rats and ameliorated diabetic neuropathy in mice." (PMID 25053869, 2014). "The relationship between the lifestyle behaviors and risk of diabetic neuropathy was mediated by cystatin C, GGT, total bilirubin, albumin, HDL-C, triglycerides, apolipoprotein A, CRP, and HbA1c with the proportion of mediation effect ranging from 3.22% to 11.35%." (PMID 36626356, 2023). "In machine learning models for predicting the onset of diabetic neuropathy, feature importance analysis of XGBoost and SVM showed that the top five variables of XGBoost were UCr, disease duration, D-dimer, CA199, and albumin." (PMID 39119009, 2024). "On the other hand, the median height, weight, blood Hb and Htc, eGFR, serum albumin, C-reactive protein, HbA1c, fasting glucose, serum total, and LDL and HDL cholesterol levels of the patients, with and without diabetic neuropathy, were significantly different (p < 0.05 for all)." (PMID 37762893, 2023).
Hyperinsulinemia (18 papers, 2012 to 2025). An increased concentration of insulin in the blood. "Hyperinsulinemia is linked to lower albumin, albumin/globulin ratio, catalase activity, glucose, and glucose/insulin ratio." (PMID 40901060, 2025). "The structural distortion and the functional impairment of the hepatic cells by NASH in the Ch Group were associated with hyperinsulinemia, high IR, and low serum protein and albumin levels." (PMID 24119413, 2013). "Some results indicate a reverse link and suggest that hyperinsulinemia caused by IR may affect serum albumin levels." (PMID 34836106, 2021). "Hyperinsulinemia-obese mares and hyperinsulinemia-light (low body weight (BW)) mares had significantly lower albumin (p = 0.0001) and albumin//globulin (p = 0.0001), but higher globulin levels (p = 0.006) compared to their respective control groups." (PMID 40901060, 2025). "Obese mares exhibited hyperinsulinemia along with reduced levels of albumin, albumin/globulin ratio, IGF-1, and glucose/insulin ratio." (PMID 40901060, 2025). "Prior research has indicated an association between serum ALB and IR, possibly attributable to the theory that compensatory hyperinsulinemia in cases of IR promotes ALB synthesis." (PMID 39345890, 2024). "Dexamethasone treatment caused hyperinsulinemia, elevated total plasma cholesterol, plasma HDL-cholesterol and also albumin levels in both pregnant and virgin rats (n = 7–9/group; p < 0.05)." (PMID 30018561, 2018). "Albumin glycation, reactive oxygen species (ROS) formation, advanced glycation end products (AGEs) accumulation and other toxins result in vascular damage and the subsequent development of albuminuria, while in the emergence of inflammation, hyperinsulinemia seems to participate as well." (PMID 37241201, 2023). "The mechanism of hyperinsulinemia, which leads to increased MAU levels, could be partly explained by the imbalance between filtered load and the tubular re-absorption of albumin." (PMID 27164093, 2016).